ATIC (5-aminoimidazole-4-carboxamide ribonucleotide formyltransferase/IMP cyclohydrolase)
Diseases named in the same sentence as ATIC in open-access papers (continued):
Sharing a sentence is not in itself a finding about the gene and the disease.
chronic hepatitis (1 paper, 2020). An active inflammatory process affecting the liver for more than six months. "Serum anti-ATIC-autoantibody was increased in HCC patients, and it also elevated in HCC-related liver diseases, including cirrhosis and chronic hepatitis." (PMID 33352757, 2020). "Another cohort composed of patients with chronic hepatitis, cirrhosis and HCC (Cohort 2) showed the anti-ATIC response, although its level is lower than that of HCC." (PMID 33352757, 2020).
colon adenocarcinoma (1 paper, 2022). "In the case of the ATIC gene, it has been proposed that its expression could be a prognostic marker for colon adenocarcinoma; its presence in small extracellular vesicles in serum is useful to differentiate early colorectal neoplasia from advanced colorectal neoplasia." (PMID 36077729, 2022).
COVID-19 (1 paper, 2022). A disease caused by infection with severe acute respiratory syndrome coronavirus 2. "The advantages of methotrexate in treating COVID-19 are summarized as follows: (a) methotrexate achieves true multi-targeting in COVID-19, by inhibiting multiple targets from diverse protein families like proteases (furin), reductases (DHFR), synthases (TYMS) and transformylase (ATIC)." (PMID 36618412, 2022).
epilepsy (1 paper, 2020). A brain disorder characterized by episodes of abnormally increased neuronal discharge resulting in transient episodes of sensory or motor neurological dysfunction, or psychic dysfunction. "Patients with ATIC mutation exhibit neurological symptoms, including profound mental retardation and epilepsy accompanied by various dysmorphic features." (PMID 32344379, 2020).
folate deficiency (1 paper, 2020). A nutritional condition produced by a deficiency of FOLIC ACID in the diet. "The GART- and ATIC-encoded enzymes or reactions were also removed from the set of reactions consuming folate which were used in the folate deficiency model." (PMID 32384607, 2020). "The modeled folate deficiency resulted in a block of purine biosynthesis, because two steps of the purine biosynthetic pathway (catalyzed by the GART and ATIC enzymes) require a folate derivative as a cofactor." (PMID 32384607, 2020). "The fact that folate deficiency and ADSL (and possibly also ATIC) deficiency both result in symptoms similar to ASD and, at the same time, exhibit very similar blocked metabolite sets, suggests a possible common pathophysiological mechanism that could lead to the development of ASD." (PMID 32384607, 2020).
Glucose intolerance (1 paper, 2018). Glucose intolerance (GI) can be defined as dysglycemia that comprises both prediabetes and diabetes. "The decreased presence of ATIC homodimers, using a small interface interactor, indeed activates AMPK and improve glucose intolerance in a mouse model." (PMID 30300385, 2018).
Hepatitis (1 paper, 2017). Inflammation of the liver. "ATIC expression was markedly associated with serum AFP level (p = 0.0011), hepatitis status (p = 0.0352), vascular invasion (p = 0.0384), histologic grade (p = 0.0006) and Tumor node metastasis (TNM) stage (p = 0.0086) in HCC patients." (PMID 29246230, 2017).
hepatitis B (1 paper, 2022). "Based on the HCC gene dataset, we used weighted gene coexpression network analysis for identifying MRGs linked to hepatitis B. An MRG prognostic index (MRGPI) with two genes, ATIC and KIF2C, was constructed using Cox regression analysis, an independent prognostic factor." (PMID 36072970, 2022).
Hyperglycemia (1 paper, 2022). An increased concentration of glucose in the blood. "No hyperglycemia was reported in ADSL-deficient patients, and only transient hypoglycemia was described in ATIC-deficient patients that was associated with increased activation of the insulin pathway in hepatocytes." (PMID 35323684, 2022).
lentivirus infection (1 paper, 2017). Virus diseases caused by the Lentivirus genus. "Effects of ATIC knockdown by lentivirus infection were evaluated on cell-proliferation, cell-apoptosis, colony formation and migration." (PMID 29246230, 2017).
viral infection (1 paper, 2020). "We also analyzed the anti-ATIC autoantibody and AFP, according to tumor-node-metastasis (TNM) staging, tumor size, and viral infection." (PMID 33352757, 2020).
tumor (31 papers, 2016 to 2025). "According to many reports, ATIC is linked to various tumor cell proliferation and drug treatment sensitivity." (PMID 36072970, 2022). "Previous studies have confirmed that the five autophagy-related genes (BIRC5, SQSTM1, HDAC1, RHEB, and ATIC) are associated with tumor proliferation, apoptosis, and resistance to anticancer agents in HCC patients." (PMID 35573678, 2022). "The expression of ATIC in liver tissues of the HCC model mouse was analyzed to validate ATIC as a tumor-associated antigen." (PMID 33352757, 2020). "Here, we have identified anti-ATIC autoantibody as a novel tumor-associated autoantibody biomarker in HCC patients." (PMID 33352757, 2020). "Moreover, ATIC has been identified as a component of tumor-associated exosomes, including bladder, ovarian, and melanoma cancer." (PMID 33352757, 2020). "In this sense, other groups have described the deficiency of ADSL and ATIC as affecting the formation and assembly of purinosome, and there is evidence that both enzymes are key in the regulation of the synthesis pathway of purines during tumor development." (PMID 30099851, 2018). "The present tumor was confirmed to have the ATIC-ALK fusion mutation." (PMID 27846861, 2016). "ATIC promotes tumor survival, proliferation, and migration by modulating the AMPK-mTOR-S6K1 signaling pathway." (PMID 41040512, 2025). "Meanwhile, ACOX1 overexpression also effectively inhibited ATIC activity in mouse xenograft tumor tissues." (PMID 36750554, 2023). "Our data demonstrated that pharmacological and genetic inhibition of ATIC, inhibits purine synthesis and tumor growth both in vivo and in vitro." (PMID 36750554, 2023). "Together, these findings suggest that ACOX1-mediated ATIC acetylation is critical for tumor suppression." (PMID 36750554, 2023). "This leads to increase KAT2B-mediated ATIC acetylation to deactivate its enzymatic activity, reduced cellular purine biosynthesis, and tumor growth inhibition." (PMID 36750554, 2023). "A recent report demonstrated that ATIC facilitates tumor growth and migration by upregulating Myc expression in LUAD." (PMID 35884522, 2022). "After the transfection of pcDNA/ATIC, the proliferation and migration of tumor cells were significantly increased." (PMID 34803509, 2021). "In our study, clinicopathological parameter sage, tumor stage, lymphatic, hematogenous metastases and SUCLG2, SUCLG1, ACLY, SUCLG2P2, ATIC and ACO2 genes were found to be associated with survival in univariable or multivariate analysis." (PMID 34589110, 2021). "Six sEV proteins were identified, namely, GCLM, KEL, APOF, CFB, PDE5A, and ATIC, which properly distinguished normal control, early neoplasia, and advanced neoplasia patients from each other." (PMID 34589434, 2021). "Consistent with the results of the enrichment analysis, ATIC knockdown affected the cell cycle of tumor cells." (PMID 34803509, 2021).
tumor (continued). "Immunohistochemistry indicated that ATIC was expressed at high levels in tumor tissues but weakly expressed in adjacent normal tissues." (PMID 34803509, 2021). "In the transplanted tumor mouse model, the growth rate of tumor cells with ATIC knockdown was significantly slower than that of control cells, and the tumor volume was significantly smaller than that of the control group." (PMID 34803509, 2021). "As a whole, these results indicate that ATIC overexpression is common in various tumors during tumor progression." (PMID 33352757, 2020). "Anti-ATIC antibodies were detected in patients with a small size of the tumor (T < 2 cm) but decreased in patients with large size tumor (T > 5 cm)." (PMID 33352757, 2020). "Differential ATIC expression was found across different tumor stages, M stages and survival outcomes." (PMID 31938577, 2020). "To explain its characteristics as a TA autoantigen, we confirmed the up-regulation of ATIC in tumor model mice and human tumor cells." (PMID 33352757, 2020). "Its specific TA antigen was identified as ATIC, a purine synthesis protein overexpressed in human tumor cells." (PMID 33352757, 2020). "Because of the similarity in antigenic sequences, TA autoantibodies generated in tumor-model mice seem to detect the ATIC protein in human tumor cells." (PMID 33352757, 2020). "Anti-ATIC antibodies were detected in patients’ sera even at early tumor stages (TNM stage 1) and increased gradually to TNM stage 4." (PMID 33352757, 2020). "Notably, PAICS and ATIC regulate critical steps in the G1-S transition and DNA replication, thus supporting rapid tumor growth." (PMID 40699765, 2025). "Knockdown of lncRNA ZFAS1/ATIC inhibited tumor growth and lung metastasis in vivo." (PMID 39001904, 2024). "We next explored the effect of ATIC K266 acetylation on tumor growth." (PMID 36750554, 2023). "Interestingly, exogenous expression of ATIC-K266Q partially promote tumor growth compared with AAV-Ctrl." (PMID 36750554, 2023). "The present study identified six sEV proteins, namely, GCLM, KEL, APOF, CFB, PDE5A, and ATIC, that could distinguish early neoplasia, advanced neoplasia, and normal controls from each other well." (PMID 34589434, 2021). "The lung metastasis ability of tumor cells was significantly reduced after ATIC knockdown." (PMID 34803509, 2021). "In contrast, all the mRNA expression levels of ATIC increased in tumor tissues (P < 0.001)." (PMID 34589110, 2021). "In conclusion, our study demonstrates the potential tumor stimulative role of ATIC in HCC." (PMID 29246230, 2017). "The first identification of AMPK-mTOR axis as a novel target of ATIC may help to understand how ATIC drives tumor progression and contribute to design of novel therapeutic strategies for human HCC." (PMID 29246230, 2017). "A RT-PCR analysis confirmed the ATIC-ALK fusion in tumor cells." (PMID 27846861, 2016). "Although the autophagy-related genes (ARGs) identified in our study did not directly overlap with classical MM driver genes such as MAF translocations, certain metabolic regulators like ATIC may indirectly assist tumor cells in adapting to the bone marrow microenvironment." (PMID 41040512, 2025). "For example, ATIC, a gene enriched in this pathway, has been reported to promote LUAD cell growth and migration by enhancing Myc expression, underscoring its role in tumor progression." (PMID 40841456, 2025). "The results of single-cell data suggested that SHMT2, ATIC and MTHFS were mainly expressed in tumor cells." (PMID 38625586, 2024). "The results showed that the expression levels of ADK, ADSL, ATIC, DPYS, ENTPD2, TXNRD1, and UCK2 in at least one tumor cell line were consistent with the predictions." (PMID 37999212, 2023).
tumor (continued). "Pearson analysis showed that SUCLG2P2, SUCLG2 and ATIC were correlated in normal COAD tissues, while only SUCLG2P2 and SUCLG2 were correlated in tumor tissues." (PMID 34589110, 2021). "Lastly, the wet-lab qRT-PCR experiments compared the mRNA expressions of PPAT, ATIC, IMPDH1, DCK, and RRM2 in between 10 pairs of human primary HCC tissues and neighboring non-tumor liver tissues." (PMID 33520699, 2020). "The analysis of ATIC and ADSL protein expression through immunohistochemistry showed much more intense expression in tumor than in healthy tissue for AC and SCC cases." (PMID 30099851, 2018). "ATIC mRNA levels in different types of human HCC samples or normal tissues were determined from Gene Expression across Normal and Tumor tissue (GENT) database." (PMID 29246230, 2017). "Additionally, in vivo research has demonstrated that knockdown of both ATIC and lncRNA ZFAS1 can inhibit tumor growth and lung metastasis." (PMID 39001904, 2024). "We also confirmed the expression levels of SUCLG2P2, SUCLG2 and ATIC mRNA in tumor and non-tumor tissues from 10 patients with CRC." (PMID 34589110, 2021). "Analyzing the downloaded TCGA data showed that the expression of ATIC was up-regulated in the tumor, and that of SUCLG2P2 was consistent with that of SUCLG2, the mRNA expression of SUCLG2P2 and SUCLG2 were down-regulated in the tumor." (PMID 34589110, 2021). "Hence, these genes might serve as molecular targets to restrict oncogenic (i.e. ATIC, BZW2) and lipogenic (i.e. CD36, PPARγ), but promote tumor suppressive (i.e. TAGLN2) activity to treat human HCC." (PMID 32559205, 2020). "XC154p1 M13 phage blocked the binding of XC154 mAb to its target antigen in tumor cells as shown by Western blot analysis or by FACS analysis, which proves that the selected cyclic peptide with high affinity to XC154mAb can mimic the specific epitope on the natural antigen ATIC." (PMID 33352757, 2020). "Moreover, ATIC could, at least partially, affect the AMPK-mTOR-S6 K1 signaling pathway, which is important tumor-related signaling pathway in HCC, by regulating de novo purine synthesis pathway." (PMID 29246230, 2017).
cancer (28 papers, 2014 to 2025). A tumor composed of atypical neoplastic, often pleomorphic cells that invade other tissues. "Over-expressed ATIC was also secreted extracellularly via the cancer-derived exosomes, which might cause auto-immune responses." (PMID 33352757, 2020). "Moreover, suppression of miR-17 may be associated with reduced cancer stemness via regulation of the purine synthesis enzyme ATIC and aldehyde dehydrogenase ALDH." (PMID 41373892, 2025). "In addition, LAMP1, ATIC was also associated with various cancers in a autophagy‐dependent manner." (PMID 33837652, 2021). "Consistent with this idea, trimetrexate, an inhibitor of DHFR, disrupted folate metabolism in cancer cells, which led to inhibition of ATIC and accumulation of ZMP." (PMID 40793247, 2025). "ATIC is a key enzyme in the purine biosynthetic pathway, which is often upregulated in cancers and catalyzes the final two critical steps in purine synthesis." (PMID 39350574, 2024). "In contrast to these agents, which directly inhibit ATIC’s enzymatic activity, Cpd14 is a peptide-based ATIC inhibitor that disrupts the enzyme’s homodimerization and thus indirectly impairs its activity and the proliferation of certain cancer cell types." (PMID 36750554, 2023). "ZMP accumulates in cancer cells treated with pemetrexed, an anti-folate drug, because the enzyme ATIC is a target of antifolates." (PMID 37628755, 2023). "ALK-mediated phosphorylation of ATIC can rescue cancer cells from cell death induced by antifolate agents." (PMID 35205374, 2022). "The inhibition of ATIC expression in cancer cells resulted in a dramatic decrease of cell proliferation and migration and in the increase of cell apoptosis." (PMID 35056904, 2021). "Although the significance of ATIC in human cancer requires further investigation, there are several studies strongly suggesting that ATIC is a good target against several different cancers." (PMID 35056904, 2021). "ALK-mediated ATIC phosphorylation can rescue cancer cells from antifolate agents induced cell death." (PMID 33520699, 2020). "Purine biosynthesis inhibitors have previously been proposed as cancer therapeutics, and our data suggest ATIC as a potential target warranting further investigation." (PMID 31139569, 2019). "AICARFT is a folate dependent catalytic site within the ATIC gene, part of the purine biosynthetic pathway, a pathway frequently upregulated in cancers." (PMID 30337562, 2018). "It will also be interesting to study the potential different roles of ATIC in different types of cancer." (PMID 29246230, 2017). "ATIC is upregulated in cancer cells, and knockdown decreases cell proliferation and migration." (PMID 36674619, 2023). "While the high concentration of drugs required is likely because the ATIC inhibitor was developed specifically for cancer treatment in mammalian cells, this result supports the notion that the purine biosynthesis pathway constitutes an interesting target to reduce biofilm formation in S. aureus." (PMID 34935415, 2021). "ATIC upregulation in cancer has been shown in various tumors." (PMID 33352757, 2020). "Depletion of ATIC or suppression of its transformylase activity significantly decreased the survival rate of cells in clonogenic survival assays, which indicates that ATIC may promote the proliferation and migration in cancer cell lines." (PMID 32807131, 2020). "Overall, our findings might lead to a breakthrough in the field of ATIC function in supporting cancer cell growth or migration." (PMID 29246230, 2017). "CGs that target ATIC may also hold potential in this pathway for cancer treatment." (PMID 39350574, 2024). "Additionally, three other NADBPs, which mutations are implicated in cancer, were found in the catalogue of FDA approved targets, namely, 5-aminoimidazole-4-carboxamide ribonucleotide formyltransferase/IMP cyclohydrolase (ATIC), androgen receptor (AR) and isocitrate dehydrogenase 2 (IDH2)." (PMID 36880517, 2023).